CRP (C-reactive protein)
Diseases named in the same sentence as CRP in open-access papers (continued):
Sharing a sentence is not in itself a finding about the gene and the disease.
COVID-19 (continued). "For biochemical profiles, measuring C-reactive protein provides an indication of inflammation and has been used to evaluate disease severity and mortality in COVID-19 patients." (PMID 39425867, 2025). "By multivariate logistic regression analysis, the death of COVID-19 patients with diabetes is positively correlated with age and CRP (p < 0.05), and has a trend towards significance with fasting blood glucose (p < 0.1)." (PMID 39886017, 2025). "When comparing individuals with severe COVID-19 to those with mild to moderate COVID-19, our results revealed considerably higher levels of acute phase reactants (CRP and ferritin) as well as LDH." (PMID 40230780, 2025). "The CRP concentrations have been previously associated with disease progression, but few studies are exploring the impact of SNPs in the CRP gene on the severity of COVID-19." (PMID 40869297, 2025). "Concerning the outcome of COVID-19 disease in our study, absolute lymphocyte count values, D-Dimer and CRP significantly differed between the two COVID-19 patients’ groups." (PMID 40807003, 2025). "One important possible mechanism is the cytokine storm and abnormally high levels of inflammatory mediators, such as C-reactive protein, tumor necrosis factor-alpha, and IL-6, seen in COVID-19 patients." (PMID 41002604, 2025). "In patients with COVID-19, C-reactive protein levels and the neutrophil-to-lymphocyte ratio have been found to be a potential predictor of mortality." (PMID 39518661, 2024). "It has been demonstrated that CRP levels are correlated with COVID-19 and bacterial pneumonia outcomes." (PMID 38304653, 2024). "NMR, NLR, CRP, IL6, PCT, and DD were identified as relevant factors associated with the risk of COVID-19-related death." (PMID 39555074, 2024). "Our study highlighted potential utility of PCT and CRP levels for differentiation between COVID-19 and non-COVID-19 sepsis patients, as well as for distinguishing between GP and GN bacterial infections in sepsis patients." (PMID 38172766, 2024). "COVID-19 patients had lower CRP (p = 0.046) and procalcitonin (p = 0.018) levels compared to SIRS/sepsis patients without this viral infection." (PMID 39311203, 2024). "This study confirms that VCO aids in the resolution of symptoms and normalization of CRP concentrations among mild-to-moderate cases of COVID-19." (PMID 38282651, 2024). "IL-6, a pro-inflammatory cytokine that can be induced by IL-1β and a significant inducer of CRP, is consistently elevated in the serum of COVID-19 patients and strongly predicts poor prognosis." (PMID 39452786, 2024). "Primary endpoints: COVID-19 diagnosis by detecting SARS-CoV-2 genome by RT-PCR; weight loss in Main group; body temperature; C-reactive protein." (PMID 38744929, 2024). "While DBP, D-dimer, and TNT values were lower in COVID-19 patients compared to the other group, CRP and ferritin values were higher." (PMID 39139171, 2024). "The results revealed that the predictive capacities of serum transgelin for critical cases and death were similar with COVID-19 severity scores, and obviously higher compared with IL-6 and CRP." (PMID 39676863, 2024). "Increasing levels of some biomarkers, i.e., neutrophils, C-reactive protein, glucose, and LDH, were significantly associated with higher COVID-19 mortality." (PMID 38541668, 2024). "Significant differences were observed in age, CT score, ICU admission or intubation, length of stay, CRP at admission, albumin levels at admission between severe and moderate COVID-19 patients (P<0.05)." (PMID 39211792, 2024). "Overall, the VCO group showed a rapid relief from symptoms of COVID-19 and a rapid reduction in mean CRP concentrations compared to the control group." (PMID 38282651, 2024). "In this study, older age, longer length of hospitalization, longer duration of mechanical ventilation, tracheostomy, diabetes, and higher levels of CRP and PCT at intubation were associated with dysphagia in patients with severe COVID-19." (PMID 38514734, 2024).
COVID-19 (continued). "The present research aimed to evaluate the impact of the leukocyte count, thrombocytes, C-reactive protein, and transaminases on the diagnosis of COVID-19 in children." (PMID 38425663, 2024). "COVID-19 is known to up-regulate acute-phase proteins such as CRP and AGP which can affect imatinib disposition." (PMID 39445010, 2024). "The baseline model included variables that are known predictors of adverse COVID-19 outcomes, such as age, CRP levels, hypertension, hyperlipidemia, and diabetes mellitus." (PMID 39449074, 2024). "The ROC curve analysis showed CRP was a poor classifier of COVID-19 clinical stage; mild/moderate vs. severe/critical (AUC = 0.574, p value = 0.028 & 95% CI = 0.508–0.639)." (PMID 39407172, 2024). "Serum ferritin, CRP, D-dimer, and procalcitonin are good predicting tools for end-organ damage and acute kidney impairment in COVID-19." (PMID 38378528, 2024). "Evidence supporting this notion comes from a retrospective study demonstrating tofacitinib's ability to lower mortality rates in COVID-19 patients with C-reactive protein (CRP) levels ranging from 60 to 150 mg/dL." (PMID 39381111, 2024). "Serum levels of complete blood count, C-reactive protein, and COVID-19 antibody at diagnosis in children infected with COVID-19 during pre-Omicron and Omicron era." (PMID 38394318, 2024). "For instance, a clinical study observed a significant decrease in C-reactive protein (CRP) - a marker of inflammation - following the administration of JHQG in COVID-19 patients, indicating a substantial anti-inflammatory response (P<0.05)." (PMID 39026676, 2024). "A progressive decrease in peripheral blood lymphocytes, an increase in IL-6, CRP, procalcitonin, and D-dimer are considered biomarkers for COVID-19 severity based on guidelines." (PMID 38601145, 2024). "This is consistent with many studies and reviews that have indicated poor outcomes in COVID-19 patients related to elevated serum levels of CRP, PCT, D-dimer, and ferritin." (PMID 39407725, 2024). "In our situation, elevated CRP levels mirrored the significant inflammation from her viral infections, specifically COVID-19, and helped assess her overall inflammatory burden." (PMID 39840216, 2024). "Biomarkers such as CRP, ferritin, NLR, and albumin were chosen for their strong associations with COVID-19 pathophysiology." (PMID 39767161, 2024). "Among the biomarkers commonly studied in the context of COVID-19, C-reactive protein (CRP) and ferritin have emerged as important indicators of disease severity and clinical outcomes in psychiatric patients." (PMID 39408010, 2024). "Multivariate logistic regression revealed that CRP level was the only independent predictor of COVID-19 severity in this cohort: p = 0.001, odds ratio (95% confidence interval) were 1.1 (1.0–1.2) (data not presented)." (PMID 39228902, 2024). "On the other hand, the COVID-19 samples exhibited higher median blood CRP values than the disease controls, indicating more pronounced inflammation in the periphery but not in the CNS." (PMID 38961383, 2024). "For example, the prognosis for patients with COVID-19 was assessed by the CRP level, which demonstrated high prognostic significance (OR: 5.78, 95% CI 2.86-11.63)." (PMID 39335587, 2024). "On the other hand, our findings indicated that CRP levels were increased in patients with severe COVID-19." (PMID 39058886, 2024). "Chemerin in the blood of various patient cohorts is positively correlated with C-reactive protein, and this was also observed in those with COVID-19." (PMID 39335612, 2024). "SARS-CoV-2 infection causes a pattern of metabolic and clinical manifestations, leading to leukocytopenia, lymphopenia, and elevated levels of C-reactive protein (CPR) in patients with the primary form of COVID-19." (PMID 38248379, 2024).
COVID-19 (continued). "The predictive value of CRP for COVID-19 severity has been highlighted in many previous studies along with other laboratory parameters, especially using machine learning and neural networking approaches for accurate prediction and deduction of decision trees." (PMID 38610151, 2024). "It has also been proven that a rapid and substantial increase in CRP predicts the development of acute respiratory failure in COVID-19 patients." (PMID 39064460, 2024). "In severe COVID-19 cases, heightened CRP levels reflect the systemic hyperinflammatory state characteristic of severe illness and are associated with a poor prognosis." (PMID 39685844, 2024). "Regarding the biomarkers, in comparison with the patients with a mild course of COVID-19, the patients with a moderate/severe course had significantly elevated serum levels of CRP (p < 0.001) and IL-6 (p = 0.007)." (PMID 39518479, 2024). "Significant positive correlations were observed between biochemical and hematological parameters in case of COVID-19 patients (CRP × N/L (r = 0.40; p < 0.05), CRP × LDH (r = 0.50; p < 0.05); ESR × LDH (r = 0.42; p < 0.05); LDH × N/L (r = 0.37; p < 0.05)." (PMID 38392603, 2024). "Our study also explored the influencing factors of COVID-19 severity, and found that eight features, including age, sex, dyspnea, comorbidity, complication, LYM, CRP, and lung injury score, were significantly associated with COVID-19 severity." (PMID 38605874, 2024). "Patients with COVID-19 usually have increased levels of serologic indicators of inflammation, such as CRP, LDH, erythrocyte sedimentation rate, and procalcitonin." (PMID 39124732, 2024). "Elevated levels of CRP and reduced albumin levels are crucial indicators of severe disease progression, indicating the development of cytokine storm in COVID-19 patients." (PMID 37712883, 2024). "The CRP remains considerably elevated even before the appearance of crucial abnormalities on CT, which is the one that correlates most strongly with COVID-19 development." (PMID 38610151, 2024). "Elevations in inflammatory markers like C-reactive protein (CRP) were also common with over a third (34.1%) of hospitalized COVID-19 cases with a CRP > 100 mg/L." (PMID 38424548, 2024). "We found a significant yet weak association between urinary protein and C-reactive protein levels (due to important variability in C-reactive protein values), suggesting the role of inflammation in kidney injury during severe COVID-19." (PMID 38899195, 2024). "CRP accounted for 32.7% of the total link between DM and poor COVID-19 prognosis, including severe pneumonia status admitting to Intensive Care Unit (ICU) and longer inpatients stay." (PMID 38455656, 2024). "According to a report, 91% of doctors weigh the CRP level when administering antibiotics to COVID-19 patients." (PMID 38773553, 2024). "Subgroup analysis excluding cancer patients showed that age, D-Dimer, CRP, and PCT were associated with 30-day mortality in COVID-19 patients, while steroid therapy is protective." (PMID 38792539, 2024). "The median values of the biomarkers related to the severity of COVID-19 (lymphocyte, D-dimer, CRP, LDH, serum ferritin, troponin-I, and KL-6), in the entire cohort were almost outside the normal range." (PMID 38277429, 2024). "Some findings from a subgroup analysis of Wuhan research showed CRP can be considered a dependable predictor of adverse outcomes in COVID-19 patients with different disease severity (AUC 0.832, z=10.23, p<0.001; AUC 0.989, z=44.04, p<0.001)." (PMID 38741892, 2024). "Our results showed that white blood cell, ALT, AST, GGT, CRE, BUN, Cys-C, CK, LDHL, ɑ-HBDH, PCT, CRP and Glu of patients with severe COVID-19 were higher than those of patients with mild and asymptomatic patients." (PMID 38360539, 2024).
COVID-19 (continued). "Our research findings also indicated that CRP has shown promising predictive performance (cutoff value = 69.9 mg/L, adjusted HR = 5.29, P < 0.001) for in-hospital mortality among all COVID-19 patients (AUC = 0.777, P < 0.001)." (PMID 38467760, 2024). "Alkaline phosphatase, lactate dehydrogenase, C reactive protein and fibrinogen were significantly higher in the COVID-19 patients with cardiovascular diseases." (PMID 38474287, 2024). "Older age, longer length of hospitalization, longer duration of mechanical ventilation, tracheostomy, diabetes, and higher levels of CRP and PCT were associated with difficulty in oral intake in patients with severe COVID-19." (PMID 38514734, 2024). "Another study suggests that procalcitonin and CRP are elevated in COVID-19 patients with secondary bacterial infections." (PMID 39273246, 2024). "Additional CRP data is reported from the Pa-COVID-19 study, Charité Universitätsmedizin Berlin with ethical approval, Berlin (EA2/066/20)." (PMID 39009040, 2024). "Patients with severe COVID-19 have been found to have elevated levels of various inflammatory markers in their blood, such as C-reactive protein (CRP), ferritin, interleukin-6 (IL-6), and others." (PMID 38814888, 2024). "A recent meta-analysis showed that probiotics were effective in reducing serum CRP and improving overall symptoms and inflammatory response in COVID-19 patients." (PMID 39324058, 2024). "Previous studies have also shown that CRP > 10 mg/dL is also related to COVID-19 hyperinflammatory syndrome and subsequent cytokine storm, often indicating more severe outcomes." (PMID 38263011, 2024). "Inflammatory biomarkers, such as IL-6 and CRP, are predictive biomarkers in COVID-19 patients and were significantly increased in the COVID-19-positive groups." (PMID 38799469, 2024). "CRP levels were significantly higher in the COVID-19 patients compared with the controls at baseline (p < 0.001)." (PMID 38337670, 2024). "As expected, COVID-19 patients presented with elevated inflammatory markers such as C-reactive protein (CRP) and leukocytosis." (PMID 38010539, 2024). "It was found that the severe COVID-19 cases showed stronger NF-κB activation, as well as higher levels of C-reactive protein (CRP), interleukin-6 (IL-6), ferritin and D-dimer." (PMID 37872376, 2024). "Thirty-four studies measured CRP levels in COVID-19 patients; 4 measured CRP levels only, while 29 measured both CRP and PCT." (PMID 39290622, 2024). "The study results suggest that Tocilizumab is effective in reducing CRP levels in severe COVID-19 group to the levels of the less complicated group at 48 h of hospitalization." (PMID 38687065, 2024). "Total ANA titers were less important than BMI, initial disease severity and age in the prediction of ongoing PASC at 21–24 weeks after COVID-19 onset, but more important than sex and early levels of CRP, IL6 and IL10." (PMID 39008486, 2024). "In line with the literature, our study also confirmed that NLR, D-Dimer, CRP, and ferritin were significantly higher in patients with severe COVID-19." (PMID 39451643, 2024). "For COVID-19 patients, C-reactive protein/albumin ratio (CAR) represented an independent predictive biomarker for in-hospital mortality." (PMID 39148011, 2024). "Another study showed that, compared with conventional treatment, the expression of CRP for patients with severe COVID-19 was significantly inhibited by an herbal Chinese decoction." (PMID 39355453, 2024). "On the other hand, study by Mondal found that serum CRP level was elevated in COVID-19 patients with DKA, similar to our findings." (PMID 38455656, 2024). "Patients with COVID-19 had a significantly higher concentration of CRP (57.66 ± 19.9 vs. 9.05 ± 15.9, p < 0.001) and procalcitonin (0.64 ± 1.57 vs. 0.03 ± 0.04, p < 0.0019) compared to the control group of subjects." (PMID 38540248, 2024). "Studies consistently show that CRP correlates with COVID-19 severity, serving as a predictive marker for adverse outcomes." (PMID 39767161, 2024).
COVID-19 (continued). "They conclude that important clinical factors associated with hospital mortality in older patients with COVID-19 include age, gender, diastolic blood pressure, body temperature, GCS score, total bilirubin, and CRP." (PMID 38622590, 2024). "The CRP is a marker of inflammation and was higher in phase 1 than phase 2, possibly due to COVID-19 patients' pre-hospital use of steroids." (PMID 38618472, 2024). "Elevated lactate dehydrogenase; C-reactive protein; age; and high expression of CD45+, CD39+CD45+, TIM3+CD39+CD4+CD45+, and TIM3+CD39+CD8+CD3+CD4+ cells were significantly associated with severe COVID-19." (PMID 38793691, 2024). "COVID-19 patients who die exhibit higher levels of troponin I, D-dimer and CRP when compared with COVID-19 survivors." (PMID 38792278, 2024). "A 16-year-old girl with fever that appeared after taking the second COVID-19 vaccine presented to the clinic with a serum creatinine of 0.89 mg/dL and C-reactive protein of 6.9 mg/dL." (PMID 37548878, 2024). "During acute inflammatory responses to COVID-19, there is usually a rapid and significant increase in serum CRP levels." (PMID 38690274, 2024). "Dysregulation of immune response mediated by IL-6 induces an elevation of CRP and ferritin levels >800 μg/L, observed in patients with severe or fatal COVID-19." (PMID 38500972, 2024). "In this study, we determined the profile of traditional biomarkers of inflammation, including CRP, albumin, complete blood count, and neopterin levels, in patients with COVID-19 admitted to the intensive care unit (ICU) and in healthy volunteers." (PMID 39058886, 2024). "The strong correlation between elevated ferritin and CRP levels and poor outcomes in COVID-19 patients suggests that these biomarkers are valuable tools in clinical practice." (PMID 39408010, 2024). "Severe COVID-19 patients displayed high levels of biomarkers for acute phase inflammation (C-reactive protein) and hypercoagulability (D-dimer)." (PMID 39475319, 2024). "The results obtained in this study lead to the conclusion that higher CRP levels are unfavorable in hospitalized COVID-19 patients." (PMID 38672113, 2024). "It was observed that patients with severe COVID-19 had higher plasma levels of C-reactive protein (CRP), IL-6, and IL-8 compared to the patients with a mild–moderate course of the disease." (PMID 39063142, 2024). "COVID-19 is often initially presented with a high level of inflammatory markers, especially C-reactive protein (CRP), thus masquerading as a bacterial infection." (PMID 38391578, 2024). "Having cardiovascular disease, diabetes, obesity, lymphopenia, dyspnea, and increased AST, ferritin, and CRP were independent predictors for ICU admission in patients with COVID-19." (PMID 38572008, 2024). "Recent studies involving admitted patients with COVID-19 also showed the utility of CRP and procalcitonin analyses to help differentiate cases of pure viral pneumonia from secondary bacterial infection." (PMID 38475703, 2024). "CRP, a fast-increasing acute inflammatory indicator, exhibited in our study the highest levels identified in COVID-19 patients to date." (PMID 38500972, 2024). "Previous studies have also shown associations of INR, creatinine, CRP, PCT, and fibrinogen with COVID-19 severity." (PMID 39408623, 2024). "COVID-19-related immune thrombosis is due to macrophage activation and cytokine storms leading to elevated CRP, ferritin and D-dimer levels, which are correlated with worse outcomes." (PMID 38317228, 2024). "A comparative study revealed that symptomatic COVID-19-positive T2DM patients had significantly higher CRP and absolute neutrophil counts and lower counts of lymphocytes and eosinophils." (PMID 39355453, 2024). "Parallel investigation results were also determined in present research, where CRP were increased in T2DM-affected COVID-19 subjects, and also depicted a strong and positive correlation with serum PAR-1 concentrations." (PMID 38675414, 2024).